URI1 (URI1 prefoldin like chaperone)
Description:
Involved in gene transcription regulation. Acts as a transcriptional repressor in concert with the corepressor UXT to regulate androgen receptor (AR) transcription. May act as a tumor suppressor to repress AR-mediated gene transcription and to inhibit anchorage-independent growth in prostate cancer cells. Required for cell survival in ovarian cancer cells. Together with UXT, associates with chromatin to the NKX3-1 promoter region. Antagonizes transcriptional modulation via hepatitis B virus X protein. Plays a central role in maintaining S6K1 signaling and BAD phosphorylation under normal growth conditions thereby protecting cells from potential deleterious effects of sustained S6K1 signaling. The URI1-PPP1CC complex acts as a central component of a negative feedback mechanism that counteracts excessive S6K1 survival signaling to BAD in response to growth factors. Mediates inhibition of PPP1CC phosphatase activity in mitochondria. Coordinates the regulation of nutrient-sensitive gene expression availability in a mTOR-dependent manner. Seems to be a scaffolding protein able to assemble a prefoldin-like complex that contains PFDs and proteins with roles in transcription and ubiquitination.
Synonyms: C19orf2; NNX3; PPP1R19; RMP; URI; FLJ10575
Tractability: PROTAC: ubiquitination databases record sites on it; its protein half-life has been measured.
Gene: Protein-coding gene on chromosome 19 (29,923,644 to 30,016,612, forward strand). Ensembl gene ENSG00000105176.
Subcellular location: Nucleus; Cytoplasm; Mitochondrion; Cell projection, dendrite
Subcellular location (Human Protein Atlas): Nucleoplasm; Cytosol
Gene Ontology:
Molecular function: chromatin binding; phosphoprotein binding; protein binding; RNA polymerase II complex binding; transcription corepressor activity; phosphatase inhibitor activity
Biological process: cellular response to growth factor stimulus; cellular response to steroid hormone stimulus; negative regulation of intrinsic apoptotic signaling pathway; negative regulation of phosphatase activity; negative regulation of transcription by RNA polymerase II; regulation of cell growth; regulation of transcription by RNA polymerase II; response to virus; protein stabilization
Cellular component: cytoplasm; cytosol; nucleoplasm; nucleus; RPAP3/R2TP/prefoldin-like complex; protein folding chaperone complex; dendrite; mitochondrion
Genetic constraint (gnomAD): Loss-of-function variants: 34 observed, 53.85 expected, observed/expected ratio (o/e) 0.63, 90% interval 0.48 to 0.84. The upper end of that interval is the gene's LOEUF score, 0.84, which puts it in group 3 of 6, group 1 being the genes least tolerant of losing a copy. Missense variants: 630 observed, 615.3 expected, observed/expected ratio (o/e) 1.02, 90% interval 0.96 to 1.09. Synonymous variants: 237 observed, 222.18 expected, observed/expected ratio (o/e) 1.07, 90% interval 0.96 to 1.19.
Homologues: Orthologues: chimpanzee URI1 (99% identical), macaque URI1 (96% identical), dog URI1 (84% identical), pig URI1 (84% identical), guinea pig URI1 (84% identical), rabbit URI1 (81% identical), mouse Uri1 (75% identical), rat Uri1 (72% identical), tropical clawed frog uri1 (58% identical), zebrafish uri1 (52% identical), Drosophila melanogaster uri (24% identical).
Diseases named in the same sentence as URI1 in open-access papers:
URI1 is named in the same sentence as 27 diseases in open-access papers, as found by Europe PMC text mining. Sharing a sentence is not in itself a finding about the gene and the disease. The quoted sentences say what the papers report.
hepatocellular carcinoma (9 papers, 2013 to 2025). A malignant tumor that arises from hepatocytes. "High expression of URI1, known to be involved in the development of hepatocellular carcinoma (HCC), is associated with poor HCC prognosis." (PMID 39794779, 2025). "URI1 has recently been identified as an oncogene in several types of cancer, including ovarian cancer and hepatocellular carcinoma." (PMID 40900789, 2025). "Unconventional prefoldin RNA polymerase II subunit 5 interactor (URI1) has emerged as an oncogenic driver in hepatocellular carcinoma (HCC)." (PMID 31739577, 2019). "Amplification and/or deregulated expression of URI1 has been observed in various cancer contexts including ovarian and hepatocellular carcinoma and multiple myeloma, supporting the view that URI1 may act as a multifaceted modifier of cancer cell proliferation and survival." (PMID 27105489, 2016).
ovarian carcinoma (7 papers, 2012 to 2025). A malignant neoplasm originating from the surface ovarian epithelium. "Additionally, a higher prevalence of gain 19q12 in patients with high-IPR score was identified, namely, locus encoded cyclin E1 (CCNE1) and URI1, and has been previously identified to be associated with chemoresistance in ovarian cancer patients." (PMID 35372049, 2022). "Ovarian cancer cells overexpress or amplify certain R2TP/PFDL subunits, such as URI1, which have been linked to tumour progression." (PMID 37124501, 2023). "BRCA1, CDKN1B, PPP1CC, SKP2, and URI1 were clustered in subnetwork 8 and categorized as shared proteins in PCOS and ovarian cancer, hence suggesting an association between the two." (PMID 31216618, 2019). "RT-qPCR analysis revealed that URI1, PAK2, PARP1, CLU, and TIMP3 were significantly upregulated, while UBB, RPL11, CAV1, NUPR1, and Hsp90ab1 were significantly downregulated in the ovarian cancer samples." (PMID 37124501, 2023). "We also found that apoptosis-related genes, URI1, PAK2, PARP1, CLU and TIMP3, were highly expressed, while immune-related genes, UBB, RPL11, CAV1, NUPR1 and Hsp90ab1, were lowly expressed in ovarian cancer cells." (PMID 37124501, 2023). "In subnetwork 8, long-term potentiation was identified as a significant pathway, where PPP1CC and PPP1CA directly interacted with three PCOS-ovarian cancer-shared PCOSrps—i.e., BRCA1, PPP1CC, and URI1—and indirectly interacted with two shared PCOSrps (CDKN1B and SKP2)." (PMID 31216618, 2019). "The URI1 gene (HGSC vs EC comparison), involved in ubiquitination and transcription, spans the same genomic region as CCNE1, and has also been reported to be amplified in ovarian carcinoma and may contribute to tumorigenesis." (PMID 32409713, 2020).
prostate carcinoma (3 papers, 2013 to 2018). A carcinoma that arises from epithelial cells of the prostate gland. "Our lab has shown that UXT knockdown reduces URI-1 protein stability in prostate cancer cells." (PMID 29649254, 2018).
colorectal cancer (2 papers, 2016 to 2019). A primary or metastatic malignant neoplasm that affects the colon or rectum. "Here, we report that human colorectal cancer (CRCs) cell lines demonstrate differential dependency on URI1 and on the URI1 partner PFD STAP1 for survival, suggesting that this differential vulnerability of CRC cells is directly linked to URI1C chaperone function." (PMID 27105489, 2016).
gastric cancer (2 papers, 2021 to 2022). A primary or metastatic malignant neoplasm involving the stomach. "It has been reported that knockout of URI1 in gastric cancer cells results in enhanced oxidative stress and DNA damage when cells was exposed to potassium dichromate 17, which means URI plays a role in maintaining redox homeostasis." (PMID 34421352, 2021). "The circRNA circURI1 back-spliced from exons 3–4 of URI1 is identified from circRNA profiling of 5 paired gastric cancer (GC) and adjacent non-cancerous (paraGC) specimens." (PMID 35427215, 2022).
Myocardial fibrosis (2 papers, 2020 to 2022). "One lncRNA, known as HOTAIR (HOX transcript antisense RNA) was associated with myocardial fibrosis via activation of the WNT signaling pathway through targeting the URI1 gene (unconventional prefoldin RPB5 interactor 1)." (PMID 32517807, 2020). "Previous studies reported that HOTAIR regulates the collagen-containing extracellular matrix through URI1 activation of the Wnt pathway in myocardial fibrosis." (PMID 35845040, 2022).
Cirrhosis (1 paper, 2019). A chronic disorder of the liver in which liver tissue becomes scarred and is partially replaced by regenerative nodules and fibrotic tissue resulting in loss of liver function. "Thus, it is also worth it to investigate whether c-MYC-induced URI1 is involved in sorafenib resistance mechanisms in HCC-B patients with decompensated cirrhosis." (PMID 31739577, 2019).
HCMV infection (1 paper, 2024). "Our findings indicate that HCMV infection disrupts PP1 function through the temporal dysregulation of at least nine recognized regulatory subunits, PPP1R10, PPP1R7, YLPM1, PPP1R11, PPP1R9A, PPP1R8 (NIPP1), PPP1R9B, PPP1R12C, and URI1." (PMID 39772267, 2024).
Hepatitis (1 paper, 2019). Inflammation of the liver. "In this context, URI1 would be an ideal target for the treatment of HCC-B because it is involved in both hepatitis and HCC." (PMID 31739577, 2019).
melanoma (1 paper, 2019). A malignant, usually aggressive tumor composed of atypical, neoplastic melanocytes. "For this purpose the BRAFV600E-mutated melanoma cell line A375-P was treated with 1 μM of the vemurafenib analogue PLX4720 for 16 h, followed by URI1 immunoprecipitation and proteomics analysis." (PMID 31123282, 2019). "Only URI1 interaction with POLR2A consistently decreased in three out of four melanoma cell lines." (PMID 31123282, 2019). "We performed a mass spectrometry analysis to investigate whether BRAFV600E oncogenic signaling might influence interactions of the URI1 chaperone complex with client proteins in melanoma cell lines." (PMID 31123282, 2019).
cancer (14 papers, 2012 to 2025). A tumor composed of atypical neoplastic, often pleomorphic cells that invade other tissues. "Given the structural and functional relationships of URI1 with molecular chaperones, we hypothesized that in this function, URI1 may help cancer cells to cope with the stress associated with oncogenic transformation." (PMID 27105489, 2016). "The upregulation of uri1 and igf1r genes is commonly observed in various cancer types, serving as a characteristic feature." (PMID 38491378, 2024). "Unconventional prefoldin RPB5 interactor 1 (URI1) exhibits characteristics similar to those oncoproteins, which promotes survival of cancer cells." (PMID 34421352, 2021). "Overexpression of URI1 in liver tumor tissue can also promote resistance to cancer therapy." (PMID 39794779, 2025). "Additionally, a recent study demonstrated how URI1-mediated cancer treatment resistance can be overcome in vitro." (PMID 39794779, 2025). "Accordingly, certain cancer cells may have evolved a specific dependency on the URI1 chaperone system for their survival." (PMID 27105489, 2016). "Additionally, URI1 expression promotes cancer cell survival and HCC metastasis." (PMID 39794779, 2025). "We found that apoptosis-related genes URI1, PAK2, PARP1, CLU, and TIMP3 were significantly upregulated in multiple cell populations of cancer cells." (PMID 37124501, 2023). "That URI1 and STAP1 act as part of the URI1C to mediate survival of a subset of CRC cell lines suggests that certain cancer cells have evolved a specific dependency on this class of molecular chaperone complexes." (PMID 27105489, 2016). "URI1 may be a ‘non-oncogene’ that supports the oncogenic phenotype of cancer cells that depend on a molecular chaperone system to survive." (PMID 37124501, 2023). "In this context, URI1 induced by c-MYC may function as a negative-feedback regulator that allows cancer cells to adapt to metabolic stress and survive under glucose deprivation." (PMID 31739577, 2019). "Thus, depending on the cancer cell context, URI1 can mediate ‘oncogene addiction’ as is the case in carcinomas with URI1 copy number increase or ‘non-oncogene addiction’ as in CRCs, marking URI1 and the URI1C attractive targets to be exploited for cancer therapy." (PMID 27105489, 2016).
tumor (6 papers, 2012 to 2023). "In the present study, we demonstrated that HCC-B tumor tissues frequently express URI1 proteins, and that HBx activates the promoter of the URI1 gene." (PMID 31739577, 2019). "In HCC-B tumor tissues, immunostaining of URI1 was also detected mainly in the cytosol, but also in the nucleus." (PMID 31739577, 2019). "We performed a chromatin immunoprecipitation (ChIP) assay in paired tumor and non-tumor liver tissues from HCC-B patients to investigate whether c-MYC plays a role in URI1 expression in HCC-B." (PMID 31739577, 2019). "It was shown that c-MYC recruitment to the E-box in the URI1 promoter region was significantly increased in HCC-B tumor tissues, compared with paired non-tumor liver tissues, suggesting that c-MYC is involved in the transcription of the URI1 gene in HCC-B." (PMID 31739577, 2019). "The positivity of URI1 expression was significantly higher in HCC-B tumor tissues than in non-HBV-related HCC tumor tissues, suggesting that a specific mechanism underlies URI1 expression in HCC-B." (PMID 31739577, 2019).
infection (2 papers, 2024 to 2025). The state of being infected such as from the introduction of a foreign agent such as serum, vaccine, antigenic substance or organism. "URI1 overexpression was confirmed at the mRNA level by RT-qPCR on day 6 and at the protein level by western blotting on days 1 and 6 after infection." (PMID 39794779, 2025). "URI1 level was analyzed one day and five days post-infection in HepG2-NTCP cells, and two and seven days post-infection in primary human hepatocytes." (PMID 39794779, 2025). "To ensure efficient URI1 silencing throughout the infection time course, we quantified URI1 mRNA levels using RT-qPCR and protein levels using western blotting." (PMID 39794779, 2025). "Previous studies have examined the effect of URI1 on HBV expression from a plasmid, whereas our study focused on viral replication following in vitro infection of human hepatocytes." (PMID 39794779, 2025). "Specifically, the interaction with PPP1R10 (PNUTS) was found to be most enriched over the course of the infection, whereas the interaction with URI1 (PPP1R19) showed the most pronounced decrease." (PMID 39772267, 2024). "Supporting the premise that URI1 is a promising therapeutic target for HCC, our findings show that URI1 knockdown does not enhance HBV infection in an acute infection model." (PMID 39794779, 2025). "Five days post-infection, URI1 mRNA levels in HepG2-NTCP cells remained reduced by 40 to 70% compared to the control, while all siRNAs tested reduced URI1 mRNA levels in PHH by approximately 70% seven days post-infection." (PMID 39794779, 2025).
URI1 also shares sentences with these, for which no sentence is quoted: breast carcinoma (3 papers); liver cancer (2); autism (1); breast tumors (1); endometrial cancer (1); endometrioid carcinomas (1); hepatitis B virus infection (1); lung carcinoma (1); multiple myeloma (1); ovarian tumor (1); pancreatic cancer (1); prostate tumors (1); radiation-induced gastrointestinal syndrome (1); uterine carcinosarcoma (1).